POLR2J3 (RNA polymerase II subunit J3)
Description:
DNA-dependent RNA polymerase catalyzes the transcription of DNA into RNA using the four ribonucleoside triphosphates as substrates. Component of RNA polymerase II which synthesizes mRNA precursors and many functional non-coding RNAs. Pol II is the central component of the basal RNA polymerase II transcription machinery. It is composed of mobile elements that move relative to each other. RPB11 is part of the core element with the central large cleft (By similarity).
Synonyms: POLR2J3-UPK3BL2
Tractability: PROTAC: ubiquitination databases record sites on it.
Gene: Protein-coding gene on chromosome 7 (102,537,918 to 102,572,653, reverse strand). Ensembl gene ENSG00000168255.
Subcellular location: Nucleus
Subcellular location (Human Protein Atlas): Nucleoplasm
Gene Ontology:
Molecular function: protein binding; DNA-directed RNA polymerase activity; DNA binding; protein dimerization activity
Biological process: transcription by RNA polymerase II; DNA-templated transcription
Cellular component: nucleus; RNA polymerase II, core complex
Genetic constraint (gnomAD): Loss-of-function variants: 0 observed, 4.5 expected, observed/expected ratio (o/e) 0, 90% interval 0 to 0.66. That is too few expected variants to judge how well the gene tolerates losing a copy. Missense variants: 3 observed, 53.08 expected, observed/expected ratio (o/e) 0.0565, 90% interval 0.025 to 0.15. Synonymous variants: 0 observed, 13.12 expected, observed/expected ratio (o/e) 0, 90% interval 0 to 0.23.
Diseases named in the same sentence as POLR2J3 in open-access papers:
POLR2J3 is named in the same sentence as 4 diseases in open-access papers, as found by Europe PMC text mining. Sharing a sentence is not in itself a finding about the gene and the disease. The quoted sentences say what the papers report.
Infertility (1 paper, 2023). "Additionally, POLR2J3, MMP17, MED17, and GATAD2A are associated with various conditions ranging from infertility to neuroinflammation." (PMID 38681774, 2023). "Upregulation of genes such as POLR2J3, MMP17, and MED17 provides insights into SARS-CoV-2 pathogenesis, suggesting potential links to conditions like infertility, cancers, and neuroinflammation." (PMID 38681774, 2023).
laryngeal carcinoma (1 paper, 2023). Carcinoma that arises from the laryngeal epithelium. "At present, our results suggest that the expression of POLR2J3 and MYH11 genes is associated with the prognosis of laryngeal cancer patients." (PMID 37598251, 2023). "Compared with adjacent tissues, POLR2J3 protein and MYH11 protein were significantly overexpressed in laryngeal cancer tissues." (PMID 37598251, 2023).
POLR2J3 also shares sentences with these, for which no sentence is quoted: breast carcinoma (1 paper); cancer (1).